DYNC1I1 (dynein cytoplasmic 1 intermediate chain 1)
Description:
Acts as one of several non-catalytic accessory components of the cytoplasmic dynein 1 complex that are thought to be involved in linking dynein to cargos and to adapter proteins that regulate dynein function. Cytoplasmic dynein 1 acts as a motor for the intracellular retrograde motility of vesicles and organelles along microtubules. The intermediate chains mediate the binding of dynein to dynactin via its 150 kDa component (p150-glued) DCTN1. May play a role in mediating the interaction of cytoplasmic dynein with membranous organelles and kinetochores.
Synonyms: DNCI1; DNCIC1
Tractability: PROTAC: its protein half-life has been measured.
Gene: Protein-coding gene on chromosome 7 (95,772,459 to 96,110,322, forward strand). Ensembl gene ENSG00000158560.
Subcellular location: Cytoplasm; Chromosome, centromere, kinetochore; Cytoplasm, cytoskeleton, spindle pole
Pathways (Reactome):
Cell Cycle: Amplification of signal from unattached kinetochores via a MAD2 inhibitory signal; EML4 and NUDC in mitotic spindle formation; Mitotic Prometaphase; Resolution of Sister Chromatid Cohesion; Separation of Sister Chromatids
Vesicle-mediated transport: COPI-independent Golgi-to-ER retrograde traffic; COPI-mediated anterograde transport
Autophagy: Aggrephagy
Cellular responses to stimuli: HSP90 chaperone cycle for steroid hormone receptors (SHR) in the presence of ligand
Disease: HCMV Early Events
Immune System: MHC class II antigen presentation
Signal Transduction: RHO GTPases Activate Formins
Gene Ontology:
Molecular function: protein binding; spectrin binding; cytoskeletal motor activity; dynein heavy chain binding; dynein light chain binding; microtubule binding; microtubule motor activity
Biological process: vesicle transport along microtubule; positive regulation of intracellular transport; positive regulation of mitotic cell cycle spindle assembly checkpoint; transport along microtubule; microtubule-based movement
Cellular component: cytoplasm; cytoplasmic ribonucleoprotein granule; kinetochore; nucleus; recycling endosome; spindle pole; vesicle; cytoplasmic dynein complex; cytosol; male germ cell nucleus; perinuclear region of cytoplasm
Genetic constraint (gnomAD): Loss-of-function variants: 41 observed, 82.25 expected, observed/expected ratio (o/e) 0.5, 90% interval 0.39 to 0.65. The upper end of that interval is the gene's LOEUF score, 0.65, which puts it in group 2 of 6, group 1 being the genes least tolerant of losing a copy. Missense variants: 569 observed, 771.1 expected, observed/expected ratio (o/e) 0.74, 90% interval 0.69 to 0.79. Synonymous variants: 245 observed, 278.15 expected, observed/expected ratio (o/e) 0.88, 90% interval 0.79 to 0.98.
Homologues: Orthologues: chimpanzee DYNC1I1 (100% identical), macaque DYNC1I1 (99% identical), pig DYNC1I1 (99% identical), dog DYNC1I1 (99% identical), mouse Dync1i1 (98% identical), rabbit DYNC1I1 (98% identical), rat Dync1i1 (98% identical), tropical clawed frog dync1i1 (89% identical), zebrafish dync1i1b (79% identical), guinea pig DYNC1I1 (61% identical), Drosophila melanogaster sw (51% identical), Drosophila melanogaster Sdic2 (46% identical), and 7 more. Paralogues in human: DYNC1I2 (78% identical), DNAI4 (20% identical), DNAI1 (18% identical), DNAI3 (18% identical), DYNC2I1 (16% identical), DNAI2 (16% identical), DYNC2I2 (16% identical).
Diseases named in the same sentence as DYNC1I1 in open-access papers:
DYNC1I1 is named in the same sentence as 40 diseases in open-access papers, as found by Europe PMC text mining. Sharing a sentence is not in itself a finding about the gene and the disease. The quoted sentences say what the papers report.
gastric cancer (8 papers, 2019 to 2023). A primary or metastatic malignant neoplasm involving the stomach. "While not linked to prostate cancer as of yet, the cytoplasmic dynein protein DYNC1I1 is associated with increased cell migration in gastric cancer, as well as shortened progression-free survival in breast cancer." (PMID 34697370, 2021). "Together, these data indicated that DYNC1I1 expression increased with the progression of gastric cancer stage, and high DYNC1I1 expression was associated with the worse outcomes in gastric cancer." (PMID 31249807, 2019). "In the current study, we found that high DYNC1I1 expression in gastric cancer is associated with poor prognosis and is an independent prognostic factor." (PMID 31249807, 2019). "This study demonstrates for the first time that DYNC1I1 is independently associated with poor prognosis in gastric cancer." (PMID 31249807, 2019). "To further explore the prognostic value of DYNC1I1 expression in gastric cancer, we analyzed the overall survival (OS) of gastric cancer patients based on the level of DYNC1I1 expression and found that high DYNC1I1 expression was associated with a shorter OS (P < 0.001)." (PMID 31249807, 2019). "Pilot studies have noted DYNC1I1 (dynein cytoplasmic 1 intermediate chain 1) was an adverse factor for the prognosis of patients with liver hepatocellular carcinoma, gastric cancer, colon cancer and glioblastoma (Gong L.-B." (PMID 35846149, 2022). "DYNC1I1 was expressed to different degrees in these cell lines, and greater expression was observed in the gastric cancer cells compared to normal gastric cells GES-1." (PMID 31249807, 2019). "It was found that IL-6 and DYNC1I1 were positively correlated in gastric cancer with a correlation coefficient of 0.53 (P < 0.05)." (PMID 31249807, 2019). "Multivariate Cox analysis revealed that DYNC1I1 was an independent prognostic indicator for gastric cancer (P < 0.05)." (PMID 31249807, 2019). "Previous studies have confirmed the effect of DYNC1I1 on the biological function of gastric cancer cells." (PMID 31605449, 2019). "The distribution of DYNC1I1 itself in the gastric cancer cells following DYNC1I1 knockdown was detected." (PMID 31249807, 2019). "By investigating the underlying mechanism of DYNC1I1 and TNPO2 in gastric cancer, the molecular markers that help in predicting the prognosis of gastric cancer were screened." (PMID 31605449, 2019). "Together, these results indicate that knockdown of DYNC1I1 suppressed cell growth and migration of gastric cancer cells by regulating the secretion of IL-6." (PMID 31249807, 2019). "DYNC1I1 was associated with deeper infiltration depth (T stage), increased lymph node metastasis (N stage), and later staging (TNM stage) in gastric cancer." (PMID 31249807, 2019). "In this study, we found that DYNC1I1 expression was upregulated in gastric cancer, and high DYNC1I1 expression was an independent prognostic factor for this disease." (PMID 31249807, 2019). "RT-qPCR and Western blot were used to verify the transient knockdown of DYNC1I1 mRNA and protein knockdown efficiency in gastric cancer cells, respectively." (PMID 31249807, 2019). "High levels of DYNC1I1 expression increased the proliferation and migration of gastric cancer cells." (PMID 31249807, 2019). "DYNC1I1, as the important binding subunit of cytoplasmic dynein, the function of it in gastric cancer needs to be further explored." (PMID 31249807, 2019). "Overall, the in vitro experiments demonstrated that knockdown of DYNC1I1 suppressed cell growth and migration of gastric cancer cells." (PMID 31249807, 2019). "In this study, we demonstrated that P65 must bind to DYNC1I1 to gain entry into the nucleus in gastric cancer cells." (PMID 31249807, 2019). "In summary, our study showed that gastric cancer patients with high DYNC1I1 expression had a poor prognosis." (PMID 31249807, 2019). "DYNC1I1 showed positive correlation with TNPO2 in gastric cancer with a correlation coefficient of 0.69 (P < 0.05)." (PMID 31605449, 2019).
gastric cancer (continued). "Our previous studies have shown that DYNC1I1 is a poor prognostic factor for gastric cancer and can promote the proliferation and metastasis of gastric cancer cells." (PMID 31605449, 2019). "The chi-square test was used to determine the relationships between DYNC1I1 expression and the clinicopathological features of gastric cancer." (PMID 31249807, 2019). "Taken together, these results showed that DYNC1I1 controls IL-6 expression levels by regulating NF-κB/p65 nuclear translocation in gastric cancer cells." (PMID 31249807, 2019). "High expression of DYNC1I1 was associated with poor prognosis and promoted the proliferation and migration of gastric cancer cells by upregulating IL-6 expression, which suggests that DYNC1I1 may be a potential therapeutic target for gastric cancer." (PMID 37628612, 2023). "We speculate that DYNC1I1 promotes the advanced staging of gastric cancer (i.e., tumor progression), which results in poor patient prognosis." (PMID 31249807, 2019). "To determine whether DYNC1I1 regulates the growth and migration of gastric cancer cell lines through the IL-6, we knocked down IL-6 in both HGC-27 and SGC-7901 cells and used qRT-PCR to verify the knockdown efficiency." (PMID 31249807, 2019). "DYNC1I1 expression and clinicopathological characteristics in 298 gastric cancer." (PMID 31249807, 2019). "The level of DYNC1I1 in gastric cancer increased with the progression of the disease." (PMID 31249807, 2019). "DYNC1I1 promoted the proliferation and migration of gastric cancer cells both in vitro and in vivo." (PMID 31249807, 2019). "Collectively, these data revealed an important role for the DYNC1I1-driven IL-6/STAT pathway in gastric cancer proliferation and migration, suggesting that DYNC1I1 may be a potential therapeutic target for gastric cancer." (PMID 31249807, 2019). "This study revealed the role of DYNC1I1 in the biological behavior of gastric cancer cells, suggesting that DYNC1I1 may be a potential therapeutic target for the treatment of gastric cancer." (PMID 31249807, 2019). "Blocking the IL-6/STAT3 axis abolished the effects of DYNC1I1 on gastric cancer cells." (PMID 31249807, 2019). "DYNC1I1 promoted the proliferation and migration of gastric cancer cells in vitro and in vivo." (PMID 31249807, 2019). "Similarly, colony formation experiments have demonstrated that overexpression of DYNC1I1 can promote long-term proliferation of gastric cancer cells." (PMID 31249807, 2019). "Hence, in this study, we initially found that the downregulation of TNPO2 mRNA expression was most significantly observed after silencing DYNC1I1 in gastric cancer cells by gene expression microarray analysis, which indicated that DYNC1I1 as a potential upstream signaling mediator of TNPO2." (PMID 31605449, 2019). "First, to verify the accuracy of the expression profile chip results, the correlation between DYNC1I1 and TNPO2 in gastric cancer was predicted by using the Gene Expression Profiling Interactive Analysis (GEPIA) website." (PMID 31605449, 2019). "Previous studies have shown that DYNC1I1 can promote the progression and metastasis of gastric cancer, colon cancer and glioblastoma, but no study has found that DYNC1I1 has a biological function in LIHC and is a prognostic factor of LIHC." (PMID 34679093, 2021). "Previous studies have shown that IL-6 is closely related to gastric cancer, but its correlation with DYNC1I1 has no reports yet." (PMID 31249807, 2019). "Furthermore, the correlation between DYNC1I1 and SP1, as well as TNPO2 and SP1 in gastric cancer was verified by the GEPIA website." (PMID 31605449, 2019). "Moreover, DYNC1I1 upregulation could also enhance its downstream TNPO2 expression through SP1 overexpression to promote the proliferation and invasion of gastric cancer cells." (PMID 35002514, 2022).
gastric cancer (continued). "DYNC1I1, the binding subunit of cytoplasmic dynein, could assist the cytoplasmic dynein-mediated transport of P65 to the nucleus, following which P65 could promote the expression of IL-6 and activate the STAT3 phosphorylation to promote the proliferation and metastasis of gastric cancer cells." (PMID 35002514, 2022).
glioblastoma (5 papers, 2019 to 2022). The most malignant astrocytic tumor (WHO grade IV). "DYNC1I1 is dramatically downregulated in patient samples of glioblastoma (GBM), where lower expression of DYNC1I1 correlates with poorer patient survival." (PMID 30250299, 2019). "At the same time, DYNC1I1 interacts with mammalian sphingosine kinase SK2 to sequester it away from the plasma membrane and promote tumor cell death in glioblastoma." (PMID 31249807, 2019). "The latest research shows that DYNC1I1 is significantly downregulated in patients with glioblastoma (GBM), and low DYNC1I1 expression is related to poor patient survival." (PMID 31249807, 2019). "Furthermore, we report a dramatic downregulation of DYNC1I1 in glioblastoma (GBM), which correlates with poorer patient survival, and demonstrate that lower DYNC1I1 expression in GBM cells coincides with more SK2 localized to the plasma membrane." (PMID 30250299, 2019).
prostate carcinoma (3 papers, 2018 to 2024). A carcinoma that arises from epithelial cells of the prostate gland. "The increased expression of EMT proteins and decrease in prostate cancer cell migration upon DYNC1I1 knockdown suggested that lysosome retrograde trafficking machinery is required to regulate EMT in prostate cancer cells." (PMID 39217195, 2024). "Although DYNC1I1 is significantly up-regulated in liver tumors but not in prostate tumors, our findings suggest that it may be the next useful prostate cancer biomarker." (PMID 29344347, 2018).
hearing loss (2 papers, 2016 to 2025). "We next examined the unbiased chromatin structure at the Dync1i1-Dlx5/6 locus on chromosome 6, which is implicated in Split-Hand/Foot Malformation Type 1 (SHFM1) and associated with hearing loss." (PMID 41169613, 2025). "Further supporting this mechanism, a pericentric inversion (chr7: 29,043,157–96,185,954) displaced DYNC1I1 exons 15 and 17 nearly 67 Mb away from DLX5/6, preventing proper enhancer-promoter interactions and leading to SHFM1 and hearing loss." (PMID 41169613, 2025). "Similarly, our analysis of the Dync1i1-Dlx5/6 locus revealed chromatin loops that overlap with deletions linked to SHFM1 (OMIM #220600) and associated hearing loss." (PMID 41169613, 2025). "Interestingly, not all SHFM1 patients with DYNC1I1 deletions experience hearing loss." (PMID 41169613, 2025).
hepatocellular carcinoma (2 papers, 2022 to 2025). A malignant tumor that arises from hepatocytes. "One research shows that DYNC1I1 gene expression was up-regulated and further led to activation of the AKT/ERK signaling pathway to promote hepatocellular carcinoma (HCC) progression." (PMID 36685979, 2022).
lymph node metastasis (2 papers, 2019 to 2020). "Moreover, the IHC score of DYNC1I1 staining was significantly increased along with lymph node metastasis and advanced TNM stage." (PMID 32195179, 2020). "Furthermore, a chi-square test showed that high DYNC1I1 expression was significantly correlated with ages (p = 0.042), PR-negative (p = 0.041), increased T stage (p < 0.001), lymph node metastasis (p = 0.007), and higher TNM stage (p < 0.001)." (PMID 32195179, 2020).
Atrophy (1 paper, 2016). Any weakening or degeneration, especially through lack of use. "Thus, to address the question of whether there is an intrinsic signaling pathway for protecting neuron from atrophy, dendritic atrophy caused by DYNC1I1 knockdown in primary hippocampal neuron is a good cellular model of neuronal atrophy arisen by motor protein dynein malfunction." (PMID 27510948, 2016).
autism (1 paper, 2025). Persistent deficits in social interaction and communication and interaction as well as a markedly restricted repertoire of activity and interest as well as repetitive patterns of behavior. "Interestingly, four related proteins, DYNC1I1, DYNC1LI1, DYNC1LI2 and DYNLRB1 were also reduced significantly in cerebellar vermis of children with autism." (PMID 40779003, 2025).
breast carcinoma (1 paper, 2020). "Another important finding of our study was that subcellular localization of GPSM2 was correlated with the expression of DYNC1I1, which indicated a poor prognosis in breast cancer." (PMID 32195179, 2020). "Examination of both GPSM2 and DYNC1I1 is necessary to establish a prognosis in breast cancer patients." (PMID 32195179, 2020). "Correlation between DYNC1I1 expression and clinical characteristics in breast cancer patients (n = 219)." (PMID 32195179, 2020). "In summary, examination of both GPSM2 and DYNC1I1 is necessary for accurate prognosis in breast cancer patients." (PMID 32195179, 2020). "GPSM2 and DYNC1I1 are known to form a complex in breast cancer cells." (PMID 32195179, 2020). "However, the clinical value of DYNC1I1 and the relationship between GPSM2 and DYNC1I1 in breast cancer is unclear." (PMID 32195179, 2020). "Correlations between GPSM2 and DYNC1I1 expression levels in patients with breast cancer." (PMID 32195179, 2020). "In our study, we demonstrated by immunoprecipitation that GPSM2 and DYNC1I1 could form a complex in breast cancer cells." (PMID 32195179, 2020). "We believe that assessment of the combination of GPSM2 and DYNC1I1 expression could be a promising biomarker and drug target for breast cancer." (PMID 32195179, 2020).
breast invasive carcinoma (1 paper, 2020). "The results demonstrated that DYNC1I1 is an independent risk factor, and may be a biomarker for the prognosis of invasive breast cancer patients." (PMID 32195179, 2020). "Next, in order to investigate the clinical value of DYNC1I1 in invasive breast cancer, we performed IHC analysis." (PMID 32195179, 2020). "Next, we explored the relationship between nuclear localization of GPSM2 and DYNC1I1 in invasive breast cancer." (PMID 32195179, 2020).
deafness (1 paper, 2023). An inherited or acquired condition characterized by the complete loss of the ability to hear from one or both ears. "In this study, we identified through SNP array a de novo 7q21 deletion involving exons 15 and 17 of DYNC1I1, but not including DLX5/6, in a patient affected by SHFM, bilateral deafness and an abnormality of the inner ear." (PMID 37628577, 2023).
gastric tumors (1 paper, 2019). "Xenograft models were used to study the role of DYNC1I1 in the occurrence and metastasis of gastric tumors in vivo." (PMID 31249807, 2019).
glioma (1 paper, 2020). A benign or malignant brain and spinal cord tumor that arises from glial cells (astrocytes, oligodendrocytes, ependymal cells). "The DYNC1I1 (dynein, cytoplasmic 1, intermediate chain 1) gene is known to be downregulated in glioma, and its low expression is correlated with poorer patient survival." (PMID 32513296, 2020).
intestinal cancer (1 paper, 2019). "Previous studies have shown that in colorectal cancer, the intestinal cancer inhibitor Calgranulin B binds to various proteins, including DYNC1I1, to inhibit tumor cell proliferation." (PMID 31249807, 2019). "DYNC1I1 can also bind to the intestinal cancer inhibitor Calgranulin B. But, it is not clear how to exert its inhibitory effect." (PMID 31249807, 2019).
lung carcinoma (1 paper, 2020). "FGFR3, LBP, LECT2, and DYNC1I1 were distinguishable markers in lung cancer." (PMID 32528533, 2020).
melanoma (1 paper, 2012). A malignant, usually aggressive tumor composed of atypical, neoplastic melanocytes. "Mutations in DYNC1I1 dynein, cytoplasmic 1, intermediate chain 1, which encodes a protein with roles in microtubule motor activity, progression through the spindle assembly checkpoint, and normal chromosome segregation were found in 3 of 17 acral melanomas." (PMID 23372575, 2012).
metastatic tumor (1 paper, 2024). "Additionally, a variant of unknown clinical significance in the DYNC1I1 gene was identified in the patient’s metastatic tumor, resulting in a frameshift, and may have influenced protein function." (PMID 39518386, 2024).
myeloma (1 paper, 2022). "Polymorphisms in genes involved in nervous system function, NFATC1, NFATC4, and EDN1 were associated with CIPN in 646 myeloma patients treated with bortezomib, as were TCF4, DYNC1I1, and GJE1 in 139 myeloma patients treated with bortezmib." (PMID 35360655, 2022).